GIP (gastric inhibitory polypeptide)
Diseases named in the same sentence as GIP in open-access papers (continued):
Sharing a sentence is not in itself a finding about the gene and the disease.
cancer (continued). "In this prospective study, none of the fasting and post-challenge levels of GIP and GLP-1 were associated with higher risk of incident first cancer; by contrast, higher levels of fasting GLP-1 were associated with lower risk of incident first cancer." (PMID 36611045, 2023). "In this explorative, population-based study of elderly participants, originally free from prevalent cancers and followed for a median of 9.9 years, we found no increased risk of incident first cancer associated with either fasting or post-OGTT challenge GIP and GLP-1." (PMID 36611045, 2023).
neurodegenerative disease (12 papers, 2013 to 2025). A disorder of the central nervous system characterized by gradual and progressive loss of neural tissue and neurologic function. "Patients that have dysfunction in the production and release of metabolic peptides like GLP-1, GIP, and PP are at a substantial risk of developing T3cDM and/or potentially developing a neurodegenerative disease like AD." (PMID 39857716, 2025). "Further research in mouse models of neurodegenerative diseases will be required to understand mechanisms that underlie the neuroprotective properties of GIP analogues." (PMID 23601582, 2013). "In fact, other incretins, such as GIP, have also shown neuroprotective effects in animal models of neurodegenerative diseases." (PMID 37333802, 2023). "Recently, the neuroprotective effect of GIP against brain damage or neurodegenerative diseases has been reported in some studies conducted with GIP analogues." (PMID 35204073, 2022). "The metabolic peptides glucagon-like peptide 1 (GLP-1), gastric inhibitor polypeptide (GIP), and pancreatic peptide (PP) will be discussed, as dysregulation within their processes can lead to the development of various inflammatory and neurodegenerative diseases." (PMID 39857716, 2025). "Novel GLP‐1/GIP mimetics have shown neuroprotective effects in animal models of neurodegenerative disease and may warrant testing in next generation clinical trials." (PMID 35128745, 2022). "The beneficial actions of GIP suggest that the use of long-lasting analogues may be an attractive therapeutic approach for the treatment of neurodegenerative diseases such as AD." (PMID 23601582, 2013).
tumor (10 papers, 2012 to 2025). "An ectopic GIP/GIPR axis in tumor somatotroph cells causes ~ 80% of cases of the paradoxical responses of GH." (PMID 37344722, 2024). "This suggests the development of a possible vicious cycle involving GH/IGF-1/GIP and their receptors in the liver, duodenum, and somatotroph tumor cells in the early stages of the disease." (PMID 37344722, 2024). "Several analogs have been developed and the preclinical studies have shown the specific tumour visualization by 111In-DTPA -GIP or 68Ga–DOTA-GIP." (PMID 35659779, 2022). "In this study, we develop a 177Lu-labeled semiconducting polymer nano-radiopharmaceutical with glucose-dependent insulinotropic polypeptide (GIP) as tumor targeting group (177Lu-SPN-GIP) for combined RT and PTT of PDAC." (PMID 34689758, 2021). "Further studies are required to select pathways activated by the GIP in these neoplasms, and to establish whether and how they can affect tumor behavior." (PMID 32498358, 2020). "Furthermore, although very low, uptake of a GIP-based tracer was demonstrated for the first time in a human beta-cell derived tumor." (PMID 29440684, 2018). "Among them, the expression of CNR2, GIP, GNGT1, NPY1R, SSTR5, and LEP in tumor tissue was significantly lower than in normal tissue, while the expression of GPSM2, and NMU was significantly highly expressed in tumor tissue." (PMID 33169793, 2020).
inflammation (5 papers, 2013 to 2024). Aberrant reaction of the microcirculation characterized by movement of fluid and leukocytes from the blood into extravascular tissues. "Here, using gain- and loss-of-function studies, we show that GIP alleviates 5-fluorouracil–induced (5FU-induced) gut inflammation, whereas genetic deletion of Gipr exacerbates the proinflammatory response to 5FU in the murine small bowel (SB)." (PMID 39723966, 2024). "For instance, orthologs for CRH and urocortins, Substance P, NPY, alpha-MSH, ghrelin and GIP have been described in zebrafish and in parallel implicated in the pathogenesis of intestinal inflammation, in mouse and human studies." (PMID 24376661, 2013). "However, the method used to quantify faecal GIP is sensitive at detecting transgressions to gluten-free diet compliance rather than quantitatively estimating variable intakes of gluten, which might be more important in a dose–response relationship with initiation of intestinal inflammation." (PMID 34861829, 2021). "Regarding GIP agonists (D-Ala2-GIP-glu-PAL), neuroprotection in MPTP-treated rats and cell cultures was confirmed through the reduction in dopaminergic neurons and an increase in the antiapoptotic protein Bcl-2 (β-cell lymphoma 2), which prevented apoptosis and reduced chronic brain inflammation." (PMID 31871617, 2019).
Kidney Disease (5 papers, 2012 to 2026). "The pathways activated by GIP warrant thorough investigation, as do the effects of GIP receptor agonists in kidney disorders." (PMID 37927592, 2023). "GIP concentrations are higher in uremic patients, and in patients with severe renal disease, GIP has a 10% to 30% lower capacity to increase insulin release." (PMID 36289848, 2022). "Furthermore, GIP has shown promise in improving determinants of nephropathy, such as diabetes and hypertension." (PMID 37927592, 2023). "Interestingly, GIP has been shown to exert anti-inflammatory effects by reducing plasma levels of IL-1β, IL-6 and TNF-α in mice, which are associated with increased severity of kidney disease." (PMID 37927592, 2023).
infection (4 papers, 2012 to 2025). The state of being infected such as from the introduction of a foreign agent such as serum, vaccine, antigenic substance or organism. "For instance, during the early/initial stage of infection, the GIP-sVSG released before a high level of IFN-γ production prevents a prominent strong pro-inflammatory immune response and hence favors parasite establishment." (PMID 29497418, 2018). "Among these two strongylid species, T. colubriformis commonly co-occurred with other GIP to produce a more severe impact compared to single infection to the host." (PMID 24502557, 2014).
neurological disorders (2 papers, 2018 to 2024). "Our current studies add to the increasing evidence that the augmentation of GIP signaling may be of clinical value for PD and other neurological disorders, warranting further investigation." (PMID 29641447, 2018).
gastrointestinal disorders (1 paper, 2025). "An increase in the concentration of the DPP4 substrates GLP-1, GIP (also called Gastric Inhibitory Polypeptide), the Pituitary Adenylate Cyclase-Activating Polypeptide (PACAP) and oxyntomoduline has been related to gastrointestinal disorders." (PMID 39861115, 2025).
neuromuscular disease (1 paper, 2024). "Regarding the secretion of incretin, GLP1, and GIP, the twenty-eight patients with DM1, excluding one missing case, were compared with five diabetic control patients with neuromuscular diseases." (PMID 39274465, 2024).
respiratory disorders (1 paper, 2024). "GLP-1 and GIP/GLP-1 receptor agonists constitute a promising opportunity for the treatment of respiratory disorders." (PMID 39768911, 2024). "Despite this, there is undoubtedly ground for further research on the use of GLP-1 and GIP/GLP-1 receptor agonists in the broad field of respiratory disease." (PMID 39768911, 2024). "Fourth, the respiratory disease patient subpopulations that would benefit the most from the treatment of the GLP-1 and GIP/GLP-1 receptor agonists must be determined." (PMID 39768911, 2024). "Based on the data presented, we can establish that the use of GLP-1 and GIP/GLP-1 receptor agonists seems to be safe and beneficial in many respiratory disorders." (PMID 39768911, 2024).
GIP also shares sentences with these, for which no sentence is quoted: coronary atherosclerosis (3 papers); hypertriglyceridemia (3); Parkinson’s (3); prostate carcinoma (3); cystic fibrosis-related diabetes (2); dementia (2); diabetic ketoacidosis (2); diabetic kidney disease (2); dumping syndrome (2); hyperuricemia (2); intracranial hypertension (2); Osteopenia (2); overnutrition (2); ST Elevation Myocardial Infarction (2); thyroid diseases (2); acute myocardial infarction (1); acute pancreatitis (1); alcoholic fatty liver disease (1); Alström Syndrome (1); anaphylaxis (1); angioedema (1); Apnea (1); autoimmune disease (1); autonomic neuropathy (1); bacterial infections (1); bipolar disorder (1); Blindness (1); cardiomyopathy (1); chronic gastritis (1); Colon Cancer (1).
A further 44 diseases each share a sentence with GIP in 1 paper.